TMEM150C (transmembrane protein 150C)
Description:
Nonselective cationic channel with high permeability to Ca(2+). Component of a mechanosensitive cation channel, confers mechanically activated (MA) currents with slow inactivation kinetics. May contribute to proprioception.
Synonyms: TTN3; DRAM4; FLJ12993
Tractability: Antibody: UniProt places it where antibodies can reach, with high confidence; its Gene Ontology location is reachable by antibodies, with high confidence; UniProt predicts a signal peptide or a membrane-spanning region. PROTAC: ubiquitination databases record sites on it.
Gene: Protein-coding gene on chromosome 4 (82,483,170 to 82,562,357, reverse strand). Ensembl gene ENSG00000249242.
Subcellular location: Cell membrane; Lysosome membrane
Gene Ontology:
Molecular function: mechanosensitive monoatomic cation channel activity
Biological process: cellular response to mechanical stimulus; proprioception; monoatomic cation transmembrane transport
Cellular component: plasma membrane; lysosomal membrane
Genetic constraint (gnomAD): Loss-of-function variants: 9 observed, 24.92 expected, observed/expected ratio (o/e) 0.36, 90% interval 0.22 to 0.63. The upper end of that interval is the gene's LOEUF score, 0.63, which puts it in group 2 of 6, group 1 being the genes least tolerant of losing a copy. Missense variants: 240 observed, 289.93 expected, observed/expected ratio (o/e) 0.83, 90% interval 0.74 to 0.92. Synonymous variants: 97 observed, 111.8 expected, observed/expected ratio (o/e) 0.87, 90% interval 0.74 to 1.03.
Homologues: Orthologues: chimpanzee TMEM150C (100% identical), macaque TMEM150C (99% identical), dog TMEM150C (98% identical), guinea pig TMEM150C (98% identical), pig TMEM150C (97% identical), rabbit TMEM150C (97% identical), rat Tmem150c (97% identical), mouse Tmem150c (96% identical), tropical clawed frog tmem150c (76% identical), zebrafish tmem150c (66% identical), Caenorhabditis elegans F11E6.6 (16% identical). Paralogues in human: TMEM150B (25% identical), TMEM150A (25% identical), DRAM2 (23% identical), DRAM1 (20% identical).
Diseases named in the same sentence as TMEM150C in open-access papers:
TMEM150C is named in the same sentence as 8 diseases in open-access papers, as found by Europe PMC text mining. Sharing a sentence is not in itself a finding about the gene and the disease. The quoted sentences say what the papers report.
breast carcinoma (2 papers, 2022). "According to their expression in breast cancer cell lines and their function in cell survival, generating mice knocked out for Tmem150c/Dram4 and/or Tmem150a/Dram5 would be beneficial to evaluate the impact of both genes in breast cancer in vivo, and potentially in other diseases." (PMID 40396042, 2022). "We first determined that TMEM150C/DRAM4 and TMEM150A/DRAM5 are significantly expressed in different breast cancer cell lines, with MDA-MB-157 cells expressing a high level of both TMEM150C/DRAM4 and TMEM150A/DRAM5." (PMID 40396042, 2022).
lung carcinoma (1 paper, 2025). "HNRNPD and its similar gene HNRNPDL have been reported to be strongly upregulated in various cancers, including lung cancer, and play key roles in inducing tumour growth and metastasis, while TMEM150C is not well studied in cancer biology." (PMID 39909829, 2025).
neuropathy (1 paper, 2021). A disorder affecting the nervous system that manifests with pain, tingling, numbness, and/or muscle weakness. "Though TMEM150C has not been previously identified to be associated with CIPN, it is biologically plausible that its impact on ion channels and pain could mediate neuropathy." (PMID 33802509, 2021).
osteosarcoma (1 paper, 2022). A usually aggressive malignant bone-forming mesenchymal neoplasm, predominantly affecting adolescents and young adults. "To assess the role of TMEM150C/DRAM4 and/or TMEM150A/DRAM5 in modulating autophagy, we overexpressed either TMEM150C/DRAM4 or TMEM150A/DRAM5 in a human osteosarcoma cell line (Saos2), which expresses an average level of TMEM150C/DRAM4 and TMEM150A/DRAM5 mRNA." (PMID 40396042, 2022).
tumor (3 papers, 2022 to 2025). "In most validated samples ZNF566, TMEM150C, ENDOU were all significantly decrease in tumor tissues than in normal tissues." (PMID 36531250, 2022). "We validated the mRNA expression levels of the 4 ferroptosis-related genes (ZNF566, TMEM150C, ENDOU, MALSU1) in the tumor tissue and adjacent tissue of 10 HNSCC patients by RT-qPCR." (PMID 36531250, 2022).
cancer (1 paper, 2025). A tumor composed of atypical neoplastic, often pleomorphic cells that invade other tissues. "However, nearby regions such as the TMEM150C gene and intergenic areas showed very few cancer‐derived changes." (PMID 39909829, 2025). "We observed a tendency for shorter fragments in the HNRNPD gene region in cancer samples, but not in TMEM150C." (PMID 39909829, 2025).
TMEM150C also shares sentences with these, for which no sentence is quoted: Hypertension (1 paper); neuroblastoma (1).